Y_RNA (Y RNA )
Gene: Miscellaneous RNA gene on chromosome 3 (88,431,191 to 88,431,309, forward strand). Ensembl gene ENSG00000207316.
Homologues: Orthologues: chimpanzee Y_RNA (100% identical). Paralogues in human: Y_RNA (83% identical), Y_RNA (82% identical), Y_RNA (81% identical), RNY1 (79% identical), Y_RNA (79% identical), RNY1P2 (78% identical), Y_RNA (78% identical), Y_RNA (77% identical), RNY1P7 (76% identical), Y_RNA (76% identical), RNY1P11 (75% identical), Y_RNA (75% identical), and 93 more.